LINC00205 (long independently transcribed non-coding RNA 205)
Synonyms: LVBU; LOC105372839; NCRNA00205
Gene: Long non-coding RNA gene on chromosome 21 (45,287,983 to 45,353,538, forward strand). Ensembl gene ENSG00000223768.
Diseases named in the same sentence as LINC00205 in open-access papers:
LINC00205 is named in the same sentence as 13 diseases in open-access papers, as found by Europe PMC text mining. Sharing a sentence is not in itself a finding about the gene and the disease. The quoted sentences say what the papers report.
lung carcinoma (4 papers, 2020 to 2022). "LINC00205, which was previously reported to promote lung cancer and liver cancer progression, was screened out (log2 (foldchange) < −0.58, p value < 0.05), confirming the reliability of this screening." (PMID 35970927, 2022). "LINC00205 also facilitates malignant phenotypes and may be a target for lung cancer." (PMID 36168326, 2022). "Recently, long intergenic non-protein coding RNA 205 (Linc00205) have been found to promote malignancy in lung cancer by recruiting the RNA-binding protein FUS to stabilize CSDE1 mRNA, which enhances lung cancer cell proliferation, apoptosis, and migration." (PMID 35179516, 2022).
gastric cancer (2 papers, 2022). A primary or metastatic malignant neoplasm involving the stomach. "LINC00205 was an overexpressed oncogene involved in tumor progression in lung, liver, gastric cancers, and retinoblastoma." (PMID 36050740, 2022).
hepatocellular carcinoma (2 papers, 2021 to 2022). A malignant tumor that arises from hepatocytes. "Interestingly, in hepatocellular carcinoma (HCC), comprehensive genome-wide analysis revealed that the expression of LINC00205, a tumor suppressor, is positively associated with OS and recurrence-free survival." (PMID 33614260, 2021).
liver cancer (2 papers, 2022). An epithelial or non-epithelial malignant neoplasm that arises from the liver. "LINC00205 has been repeatedly proven to be involved in the progression of liver cancer through mutual regulation with miRNA and can be used as a biomarker for prognosis assessment and a potential target for disease diagnosis and treatment." (PMID 36452343, 2022).
pancreatic cancer (2 papers, 2020 to 2021). "In contrast, LINC00205 overexpression in pancreatic cancer was significantly associated with better survival." (PMID 32718068, 2020). "In addition, LINC00205 can act as a protective factor in pancreatic cancer [HR = 0.58, P (log rank) = 0.0091]." (PMID 33614260, 2021).
tumor (6 papers, 2021 to 2023). "In a xenograft mouse model of HCC, overexpression of EPHX1 decreased tumor growth, while LINC00205 silencing promoted tumor growth, confirming the in vitro data." (PMID 37111734, 2023). "And, we found that the expression of LINC00205 was significantly higher in tumor tissues than in adjacent tissues." (PMID 35013132, 2022). "The expression of Linc00205 in HB tissues was found to be remarkably higher compared to adjacent non-tumor tissues (***p<0.001)." (PMID 35179516, 2022). "We also administered a subcutaneous injection of HB cells that were transfected with either si-Linc00205 or Linc00205 ov to mice in order to induce tumor formation." (PMID 35179516, 2022). "IncuCyte system for live-cell imaging and analysis was used to determine tumor cell proliferation activity, and knockdown of LINC00205 was consistently reduced the number of proliferating cells in both BGC823 and MKN28 cell lines, compared with the control cells after 3 days." (PMID 35013132, 2022). "Our results for the first time confirmed that miR-26a was a direct target of LINC00205 and might have the potential to become a plasma marker for clinical tumor diagnosis." (PMID 35013132, 2022). "Next, we evaluated the effect of LINC00205 knockdown on tumor metastatic colonization in nude mice." (PMID 35013132, 2022). "Furthermore, knockdown of Linc00205 expression contributes to inhibition of HB cell proliferation, migration and invasion in vitro, as well as reducing tumor volumes in vivo." (PMID 35179516, 2022). "All results indicated that regulating Linc00205 can interact with miR-154-3p and ROCK1 to help produce a massive impact on tumor progression and metastasis through the MAPK signaling pathway, EMT pathway, cell cycle-related pathway and apoptosis-related pathway." (PMID 35179516, 2022).
cancer (4 papers, 2020 to 2021). A tumor composed of atypical neoplastic, often pleomorphic cells that invade other tissues. "The reported role and therefore prognostic prediction value of LINC00205 in various cancers shows significant discrepancies." (PMID 33614260, 2021). "Moreover, they significantly regulated more cancer hallmark pathways than TE‐associated lncRNAs, such as LINC00094, LINC00205, and RUSC1‐AS1." (PMID 32460441, 2020).
LINC00205 also shares sentences with these, for which no sentence is quoted: hepatoblastoma (2 papers); retinoblastoma (2); cervical cancer (1); glioma (1); prostate carcinoma (1); thyroid cancer (1).